TRAJ18 (T cell receptor alpha joining 18)
Gene: T-cell receptor joining (J) gene on chromosome 14 (22,525,650 to 22,525,715, forward strand). Ensembl gene ENSG00000211871.
Homologues: Orthologues: macaque TRAJ18 (91% identical).
Diseases named in the same sentence as TRAJ18 in open-access papers:
TRAJ18 is named in the same sentence as 6 diseases in open-access papers, as found by Europe PMC text mining. Sharing a sentence is not in itself a finding about the gene and the disease. The quoted sentences say what the papers report.
Obesity (3 papers, 2017 to 2024). Accumulation of substantial excess body fat. "Taken together, the novel Traj18−/− mouse strain exhibits ameliorated metabolic phenotypes, which is consistent with a pathogenic role of iNKT cells in the development of obesity and insulin-resistance." (PMID 28986544, 2017). "Using this new mouse strain, we re-assessed the contribution of iNKT cells to obesity and its associated metabolic abnormalities, and found that Traj18–deficient mice showed reduced weight gain and ameliorated metabolic parameters." (PMID 28986544, 2017). "Considering the potential role of MAIT cells and other T cell subsets in obesity, results obtained with the original Traj18−/− mouse model should be interpreted with caution." (PMID 29963043, 2018). "In addition to the new findings with Traj18−/− (1-1 L) mice, we observed similar weight gain curves for Traj18−/− (1-1 L) and Cd1d−/− mice on HFD, which would be consistent with a limited role of type 2 NKT cells in the development of obesity." (PMID 28986544, 2017).
tumor (3 papers, 2021 to 2023). "Interestingly, VJDT monotherapy induced expansion of an iNKT cluster classified by the expression of Cxcl10, Icos, Traj18, and Klra5, while combinational treatment, which yielded the lowest tumor volumes, showed an increased presence of both MAIT cells and Rorc-expressing DNTαβ cells." (PMID 37651197, 2023). "As predicted, C24:2 did activate type I NKT cells in vivo, and Traj18-KO mice failed to be protected against the CT26 tumor." (PMID 38127463, 2023). "As predicted, no tumor protection was induced by C24:2 in Traj18-KO mice (note that the absence of type I NKT cells in Traj18-KO mice did not affect CD1d expression)." (PMID 38127463, 2023).
TRAJ18 also shares sentences with these, for which no sentence is quoted: COVID-19 (1 paper); Hepatic steatosis (1); Insulin resistance (1); viral infection (1).